LIPA (lipase A, lysosomal acid type)
Description:
Catalyzes the deacylation of cholesteryl ester core lipids of endocytosed low density lipoproteins to generate free fatty acids and cholesterol. Hydrolyzes triglycerides (1,2,3-triacylglycerol) and diglycerides (such as 1,2-diacylglycerol and 1,3-diacylglycerol) with preference for the acyl moieties at the sn-1 or sn-3 positions.
Synonyms: LAL; CESD
Tractability: Small molecule: a high-quality ligand is known; it belongs to a druggable protein family. Antibody: UniProt predicts a signal peptide or a membrane-spanning region. PROTAC: ubiquitination databases record sites on it; its protein half-life has been measured; a small molecule that binds it is known.
Target class: Enzyme; Hydrolase
Gene: Protein-coding gene on chromosome 10 (89,212,830 to 89,415,367, reverse strand). Ensembl gene ENSG00000107798.
Subcellular location: Lysosome
Subcellular location (Human Protein Atlas): Cytosol; Vesicles; Nucleoli fibrillar center; Nucleoplasm
Pathways (Reactome):
Transport of small molecules: LDL clearance
Gene Ontology:
Molecular function: lipase activity; sterol ester esterase activity; carboxylic ester hydrolase activity; diacylglycerol lipase activity; hydrolase activity, acting on ester bonds; triacylglycerol lipase activity
Biological process: low-density lipoprotein particle clearance; sterol metabolic process
Cellular component: lysosomal lumen; lysosome
Genetic constraint (gnomAD): Loss-of-function variants: 21 observed, 21.96 expected, observed/expected ratio (o/e) 0.96, 90% interval 0.68 to 1.38. The upper end of that interval is the gene's LOEUF score, 1.38, which puts it in group 5 of 6, group 1 being the genes least tolerant of losing a copy. Missense variants: 289 observed, 320.38 expected, observed/expected ratio (o/e) 0.9, 90% interval 0.82 to 0.99. Synonymous variants: 122 observed, 119.52 expected, observed/expected ratio (o/e) 1.02, 90% interval 0.88 to 1.19.
Gene-disease validity (ClinGen):
ClinGen rates the evidence that LIPA causes each of these diseases.
lysosomal acid lipase deficiency (autosomal recessive): Definitive.
Homologues: Orthologues: chimpanzee LIPA (100% identical), macaque LIPA (98% identical), pig LIPA (83% identical), rabbit LIPA (83% identical), dog LIPA (78% identical), guinea pig LIPA (77% identical), rat Lipa (75% identical), mouse Lipa (74% identical), tropical clawed frog lipa (65% identical), zebrafish lipf (61% identical), Caenorhabditis elegans lipl-5 (42% identical), Caenorhabditis elegans lipl-1 (41% identical), and 26 more. Paralogues in human: LIPM (61% identical), LIPF (57% identical), LIPK (56% identical), LIPN (53% identical), LIPJ (49% identical).
Diseases named in the same sentence as LIPA in open-access papers:
LIPA is named in the same sentence as 155 diseases in open-access papers, as found by Europe PMC text mining. Sharing a sentence is not in itself a finding about the gene and the disease. The quoted sentences say what the papers report.
Wolman disease (73 papers, 2005 to 2026). Wolman disease represents the most severe manifestation of lysosomal acid lipase deficiency. "Infantile-onset lysosomal acid lipase deficiency (LAL-D) (Wolman disease, historically) is a rare inherited, rapidly progressive disorder caused by pathogenic variants in the LIPA gene, which encodes the enzyme LAL." (PMID 41599846, 2026). "Wolman’s disease, caused by biallelic pathogenic variants in the LIPA gene, exhibits a variety of symptoms, including an enlarged liver and failure, splenomegaly, anemia, low muscle tone, and developmental delay." (PMID 38354786, 2024). "Wolman’s disease or cholesterol ester storage disease is caused by a deficiency of lysosomal acid lipase A (LIPA)." (PMID 38354786, 2024). "The genetic analysis revealed after his demise was compatible with Wolman disease, introducing a novel mutation in LIPA gene: exon 4: NM_001127605: c." (PMID 37641143, 2023). "Mutations inactivating LIPA result in lysosomal accumulation of cholesteryl esters (Wolman disease), which damages steroidogenic cells, reducing steroidogenesis." (PMID 37445796, 2023). "Null LIPA gene mutations cause Wolman disease (WD), a fatal disease of infancy named after Moshe Wolman, who reported one of the first cases." (PMID 36092360, 2022). "Mutations in LIPA lead to lysosomal acid lipase deficiency, which can manifest as two clinical spectra: Wolman disease, which affects infants, and cholesteryl ester storage disease (CESD), which has a later onset." (PMID 35821816, 2022). "Mutations in LIPA leading to reduced LAL activity present as two rare disorders, Wolman Disease (WD) and Cholesteryl Ester Storage Disease (CESD)." (PMID 36204319, 2022). "LIPA encodes the enzyme lysosomal acid lipase, and its deficiency leads to Wolman disease in infants, which is a lysosomal storage disease characterized by the accumulation of cholesterol esters." (PMID 35455931, 2022). "Wolman disease is caused by the biallelic inheritance of pathogenic variants in the LIPA gene on chromosome 10q23.2-23.3." (PMID 34020687, 2021). "Wolman disease (primary xanthomatosis) results from disruption of lysosomal acid lipase (LIPA), and is associated with AI (often with adrenal calcifications), failure to thrive, hepatosplenomegaly and anemia in the first few months of life." (PMID 33381483, 2020). "LIPA encodes the enzyme lysosomal acid lipase, deficiency in which leads to Wolman disease in infants, a lysosomal storage disease characterised by accumulation of cholesterol esters." (PMID 29421651, 2018). "Wolman disease (WD) is a rare lysosomal storage disorder that is caused by mutations in the LIPA gene encoding lysosomal acid lipase (LAL)." (PMID 28659158, 2017). "Mutations in the LIPA gene cause lysosomal storage diseases such as Wolman disease and cholesteryl ester storage disease." (PMID 28642584, 2017). "Humans carrying mutations in LIPA, which cause partial or complete inactivation of the protein, exhibit phenotypes known as CE storage disease or Wolman disease, respectively." (PMID 27354281, 2016). "In Wolman disease, which is caused by the most severe alterations affecting the LIPA gene (nonsense mutations, frameshift defects, ect...), patients typically develop symptoms at 2–4 months of age and usually die before age 12 months." (PMID 27219619, 2016). "Mutations in LIPA cause Wolman's disease, a rare disorder characterized by accumulation of these lipids in multiple organs." (PMID 21966275, 2011). "There is only one report of CH25H deficiency in human, but the disorder presented with combined deficiency of the adjacent gene lysosomal acid lipase (LIPA), and the first patient was initially diagnosed with Wolman disease (infantile onset lysosomal acid lipase deficiency)." (PMID 31698146, 2020).
Wolman disease (continued). "Furthermore, oligomeric α-synuclein associated with PD development is increased in plasma from patients with Gaucher's disease, NPC and also Wolman disease (infant lysosomal acid lipase, LIPA, deficiency), yet another lysosomal storage disorder." (PMID 31839688, 2019). "Additionally, mutations in the LIPA gene are the cause of Wolman’s Disease, Cholesteryl ester storage disease, hyperlipidemia, premature cardiovascular disease, and increased risk for atherosclerosis." (PMID 27827461, 2016). "Disease-causing mutations in the LAL gene (lysosomal acid lipase gene [LIPA]) may result in the clinical presentation of CESD or Wolman disease (WD)." (PMID 25722898, 2015). "LIPA gene mutations may cause the cholesteryl ester storage disease and Wolman’s disease, which often accompany premature CVD." (PMID 23653095, 2013). "Given the suspicion of a lysosomal storage disorder, genetic testing identified a homozygous nonsense mutation in LIPA, and enzymatic analysis confirmed markedly reduced LAL activity, establishing the diagnosis of Wolman disease." (PMID 41869254, 2026). "Wolman disease is a rare autosomal recessive lysosomal storage disorder caused by mutations in the LIPA gene, resulting in lysosomal acid lipase (LAL) deficiency and subsequent accumulation of triglycerides and cholesterol esters in multiple organs." (PMID 41869254, 2026). "Pathogenic variants in the LIPA gene are associated with Cholesteryl Ester Storage Disease (CESD) and Wolman disease, both autosomal recessive allelic disorders (OMIM # 278000) associated with reduced activity and genetic defects of lysosomal acid lipase." (PMID 36185161, 2022). "LAL deficiency due to mutations in the LAL gene (LIPA) results in accumulation of TGs and cholesterol esters in various tissues of the body leading to pathological conditions such as Wolman’s disease and CE storage disease (CESD)." (PMID 32482718, 2020). "LAL deficiency (LAL-d), i.e., Wolman disease and cholesteryl ester storage disease (CESD), is an autosomal recessive disease in which patients are homozygous or compound heterozygous for LIPA gene mutations." (PMID 27219619, 2016). "Whereas a loss of function mutation in the LIPA gene causes Wolman disease, CESD results when residual activity of the LAL enzyme is retained." (PMID 26137452, 2015). "Lysosomal acid lipase deficiency (LALD) varies from a severe infantile-onset form (Wolman disease) to a late-onset form known as cholesteryl ester storage disease (CESD), both of which are autosomal recessive disorders caused by biallelic LIPA pathogenic variants." (PMID 39201333, 2024). "Wolman disease is a rare disease caused by the absence of functional liposomal acid lipase due to mutations in LIPA gene." (PMID 37641143, 2023). "Cholestane‐3β,5α,6β‐triol is elevated in the circulation people with Niemann–Pick type C and type B disease and also those with lysosomal acid lipase (LIPA, EC:3.1.1.13) deficiency, known as Wolman disease when there is a complete absence of the enzyme." (PMID 33506652, 2021). "Wolman Disease and cholesteryl ester storage disease (CESD) are rare entities caused by complete or partial lysosomal acid lipase (LAL) deficiency, which is encoded by the LIPA gene located at 10q23.31." (PMID 29091130, 2018). "Loss-of-function mutations in LIPA cause either the rare autosomal recessive LAL deficiencies Wolman disease, where individuals possess negligible or no LAL activity, or CE storage disease, where patients retain some residual LAL activity." (PMID 28279971, 2017). "Mutations of LIPA result in complete deficiency of LAL in patients with Wolman disease, which is fatal in the first year of life without LAL replacement, or near-total and non-fatal deficiency known as Cholesteryl Ester Storage Disease (CESD)." (PMID 25699256, 2015).
Wolman disease (continued). "The most severe form of CESD, known as Wolman disease, results from LIPA mutations that cause nearly complete absence of LAL activity and presents during infancy with hepatosplenomegaly, cholestasis, intestinal malabsorption, adrenal calcifications, and diffuse xanthomatosis." (PMID 25025052, 2014). "Wolman disease is a rare, lysosomal storage disorder in which biallelic variants in the LIPA gene result in reduced or complete lack of lysosomal acid lipase." (PMID 34020687, 2021). "Wolman disease is a severe, early-onset presentation caused by a mutation in the LIPA gene that results in the absence of LAL activity." (PMID 25722898, 2015). "In human, LIPA deficiency results in two major phenotypes of cholesterol ester storage disease (CESD; Mendelian Inheritance in Man, MIM, number: 278000): infant-onset Wolman disease, where there is no or <1% of normal LIPA activity, and late-onset CESD." (PMID 34953867, 2022).
cholesteryl ester storage disease (44 papers, 2005 to 2025). A form of lysosomal acid lipase deficiency characterized by progressive cholesterol esters and triglyceride accumulation in tissues and organs typically presenting with hepatosplenomegaly, liver dysfunction and/or dyslipidemia. "Pathogenic variants in the LIPA result in autosomal recessive Wolman disease and cholesteryl ester storage disease (CESD)." (PMID 37543928, 2023). "Cholesterol ester storage disease (CESD) is an autosomal recessive illness that results from mutations in the LIPA gene encoding lysosomal acid lipase." (PMID 16255772, 2005). "For instance, cholesteryl ester storage disease (CESD) is an autosomal recessive lysosomal storage disorder caused by various mutations in the lipase A (LIPA) gene." (PMID 40340648, 2025). "Partial loss of function LIPA mutations, usually with 1%–12% of normal activity, give rise to cholesteryl ester storage disease (CESD), a later onset, less severe disease form." (PMID 36092360, 2022). "Autosomal recessive cholesteryl ester storage disease (CESD) is caused by mutations of the lysosomal acid lipase (LIPA) gene." (PMID 34829957, 2021). "Reduced LIPA activity causes a less dramatic disease known as cholesteryl ester storage disease (CESD), which is accompanied by a build-up of fatty liver, liver fibrosis or cirrhosis and swelling of the spleen." (PMID 22936112, 2012). "Human LIPA loss of function is often considered a major cause of recessive lysosomal diseases such as Wolman disease (WOD) and cholesteryl ester storage disease (CESD)." (PMID 38338678, 2024).
lysosomal storage disorder (26 papers, 2016 to 2026). "C. elegans LIPLs are predicted to be orthologs of several human lipases, including hLAL/LIPA that is expressed in mammalian immune cells such as macrophages and is implicated in macrophage dysfunction, inflammatory signaling and lysosomal storage diseases." (PMID 41385585, 2025). "Lysosomal acid lipase deficiency (LAL-D) is an autosomal recessive ultrarare lysosomal storage disease caused by pathogenic/likely pathogenic variants in the LIPA gene." (PMID 41345659, 2025). "Lysosomal acid lipase deficiency (LAL-D) is an autosomal recessive lysosomal storage disorder, caused by homozygous or compound heterozygous pathogenic variants in the LIPA gene." (PMID 35903350, 2022). "Lysosomal acid lipase deficiency (LAL-D) is an autosomal recessive lysosomal storage disorder, caused by homozygous or compound heterozygous disease-causing variants in the LIPA gene located on chromosome 10q23.2." (PMID 35903350, 2022). "Another rare familial cause of NASH cirrhosis is the deficiency of lysosomal acid lipase (LIPA), an autosomal recessive lysosomal storage disease caused by loss-of-function mutations within the LIPA gene." (PMID 30355853, 2018). "Lysosomal acid lipase (LAL) deficiency is an autosomal recessive lysosomal storage disorder caused by mutations in the LIPA gene that leads to premature organ damage and mortality." (PMID 29527374, 2018). "Genetic mutations of human LAL (also known as LIPA) cause an autosomal recessive lysosomal storage disorder with accumulation of CE predominantly in hepatocytes, adrenal glands, intestine and cells of the monocyte-macrophage system throughout the body." (PMID 27153842, 2016). "Lysosomal acid lipase deficiency (LAL-D; OMIM # 278,000) is an ultrarare autosomal recessive lysosomal storage disorder caused by pathogenic variants in the LIPA gene (OMIM #613497), which encodes the lysosomal acid lipase (LAL) enzyme." (PMID 41345659, 2025). "Deficiency of the LAL enzyme encoded by the LIPA gene leads to LAL deficiency (LAL-D) (OMIM 278000), one of the lysosomal storage disorders involving 50–60 genes." (PMID 36555187, 2022). "Lysosomal acid lipase (LAL, EC 3.1.1.13) deficiency (LALD, MIM 278000) is an ultrarare lysosomal storage disease (LSD) associated with bi-allelic LIPA pathogenic variants causing strongly decreased LAL activity." (PMID 34906190, 2021). "Lysosomal acid lipase deficiency (LAL‐D) is a rare autosomal recessive lysosomal storage disorder caused by pathogenic variants in LIPA, resulting in diminished or absent LAL activity." (PMID 40781810, 2025). "Mutations in the LAL-encoding LIPA gene result in rare lysosomal storage disorders (LSDs)with the complete or partial absence of LAL activity." (PMID 38422518, 2024).
atherosclerosis (22 papers, 2013 to 2025). A disease characterized by the build-up of fatty material and calcium deposition in the arterial wall resulting in partial or complete occlusion of the arterial lumen. "In this review we summarize recent knowledge about the nature of LAL, mutations in LIPA leading to WD and CESD, the value of LIPA as a predictor of risk for atherosclerosis, and recent findings regarding its role in atherosclerosis and fatty liver disease." (PMID 36204319, 2022). "The relevance of our observations linking LIPA activity and efferocytosis to atherosclerosis needs to be further investigated, as multiple studies reported a correlation between LIPA variants and coronary artery disease." (PMID 39649554, 2020). "High levels of NCEH1 and LIPA have been shown to protect against atherosclerosis, and they are associated with increased cholesterol efflux." (PMID 30545366, 2018). "We were unable to identify any previously reported heart-specific phenotypes in Lipa KO models outside atherosclerosis-based studies, although polymorphisms in LIPA that increase expression are associated with impaired endothelial function and increased susceptibility to coronary artery disease." (PMID 34624333, 2021). "In addition to the top 3 crucial genes, other genes, such as the LIPA gene, also play important roles in atherosclerosis by encoding lysosomal acid lipase (LAL)." (PMID 33613306, 2021). "Loss-of-function mutations in LIPA result in accelerated atherosclerosis." (PMID 28279971, 2017). "Higher genetically proxied monocyte expression of LIPA was associated with a higher risk of both CAD and LAS, highlighting its role in the development of atherosclerosis." (PMID 40555237, 2025). "Our understanding of the transcriptional regulation of LIPA in the artery wall during the progression of atherosclerosis is far from complete." (PMID 25699256, 2015). "This dual role—where reduced LIPA activity leads to hyperlipidemia-driven atherosclerosis and elevated LIPA expression may drive pro-inflammatory actions in macrophages—highlights the importance of LIPA homeostasis in preventing atherosclerosis." (PMID 40555237, 2025). "As loss-of-function mutations in LIPA result in increased atherosclerosis in humans and overexpression of LIPA reduces atherosclerosis in mouse, the common CAD-associated variants in LIPA might be expected to cause a reduction in the levels of active LAL." (PMID 28279971, 2017). "The rs1412444 and rs2246833 polymorphisms of the LIPA gene were genotyped by 5′ exonuclease TaqMan genotyping assays in a sample of 899 Mexican patients with premature CAD, 270 individuals with subclinical atherosclerosis, and 677 healthy unrelated controls." (PMID 24069331, 2013). "This increase might enhance intracellular release of fatty acids and cholesterol via the lysosomal route, explaining the role of LIPA in atherosclerosis." (PMID 24069331, 2013). "TFEB overexpression has been shown to increase LIPA expression and lysosomal biogenesis in mouse peritoneal macrophages, and to reduce atherosclerosis in a mouse model; whether the significantly lower LIPA expression in SMCs could be similarly enhanced requires further investigation." (PMID 36204319, 2022). "More recently, expression of LIPA/LAL has been found to be low in arterial smooth muscle cells of both humans and mice, as a natural occurrence rather than due to mutations, and is the apparent cause of CE overload in lysosomes of smooth muscle cell foam cells in atherosclerosis." (PMID 36204319, 2022). "GWAS suggests functions for LIPA related to CAD and ischemic cardiomyopathy, while LDB2 has been demonstrated to be involved in the development of atherosclerosis." (PMID 37745713, 2023).